TTTY3B (testis expressed transcript, Y-linked 3B)
Synonyms: LNCRNA00122; NCRNA00122
Gene: Long non-coding RNA gene on chromosome Y (23,936,727 to 23,941,622, reverse strand). Ensembl gene ENSG00000280961.
Homologues: Paralogues in human: TTTY3 (100% identical).